ALMS1P1 (ALMS1 pseudogene 1 )
Synonyms: ALMS1L; ALMS1P
Gene: Long non-coding RNA gene on chromosome 2 (73,640,723 to 73,721,352, forward strand). Ensembl gene ENSG00000290727.
Diseases named in the same sentence as ALMS1P1 in open-access papers:
ALMS1P1 is named in the same sentence as 1 disease in open-access papers, as found by Europe PMC text mining. Sharing a sentence is not in itself a finding about the gene and the disease.
ALMS1P1 shares sentences with these, for which no sentence is quoted: pancreatic carcinoma (1 paper).